KIF20A (kinesin family member 20A)
Diseases named in the same sentence as KIF20A in open-access papers (continued):
Sharing a sentence is not in itself a finding about the gene and the disease.
pancreatic cancer (37 papers, 2011 to 2025). "In another study of pancreatic cancer, it was proved that KIF20A-10-66 peptide was a new HLA-A24 restricted tumor associated antigen, and can be used in CTL induced tumor therapy." (PMID 36798768, 2023). "KIF20A was a promising tumor-associated antigen in the treatment of pancreatic cancer." (PMID 36798768, 2023). "KIF20A is associated with progression of pancreatic cancer, but this gene might be play key role in progression of pituitary prolactinoma." (PMID 33709028, 2021). "Similarly, studies have implicated KIF20A expression in pancreatic cancer, human bladder tumors, gastric tumors, head and neck malignant tumors, and lung cancers." (PMID 27941992, 2016). "Previous reports have indicated that KIF20A is highly upregulated in various cancer cell types, including pancreatic cancer, melanoma, bladder cancer, and HCC." (PMID 40136455, 2025). "Phase I/II trials of KIF20A-derived peptide vaccines show promise in pancreatic cancer, highlighting its immunogenic potential." (PMID 41267030, 2025). "Overexpression of KIF20A in pancreatic tumors typically correlates with increased invasiveness and poor prognosis, suggesting its potential as a therapeutic target." (PMID 41008826, 2025). "In another study, KIF20A colocalized with discs large MAGUK scaffold protein 5 (DLG5) in pancreatic cancer, a protein known to interact with cell cycle regulators and implicated in tumorigenesis." (PMID 41392981, 2025). "This evidence suggests a broader applicability of KIF20A in immunotherapy beyond pancreatic cancer, hinting at a multi-cancer target potential." (PMID 39272816, 2024). "Immunogenic potential of KIF20a has been proven by the creation of HLA-A2 restricted TCRs against pancreatic cancer." (PMID 36768616, 2023). "Overexpression of KIF20A enhances resistance to chemotherapy while KIF20A inhibition reduces cell proliferation, migration and invasion of pancreatic cancer cells in PDAC." (PMID 36998446, 2023). "Based on this study, a phase I/II clinical trial was conducted to confirm the efficacy of KIF20A-66 (KIF20A-10–66) peptide in immunotherapy for patients with advanced pancreatic cancer (clinical trial registration: UMIN-CTR, number UMIN000004919)." (PMID 36798768, 2023). "KIF20A was weakly expressed in testis and thymus, highly expressed in pancreatic cancer, skin, peritoneal metastases, and other human leukocyte antigen (HLA)-A2 positive cancer cell lines." (PMID 36798768, 2023). "A phase I clinical trial combining KIF20A derived peptide with gemcitabine (GEM) was conducted in patients with advanced pancreatic cancer who had received chemotherapy and/or radiotherapy." (PMID 36798768, 2023). "Another phase I clinical trial used 4 peptides as vaccine in advanced pancreatic cancer, including KIF20A." (PMID 36798768, 2023). "The efficacies of KIF20A-derived peptides combined with Gemcitabine were evaluated in a phase I clinical trial involving advanced pancreatic cancer patients who had previously received chemotherapy and radiotherapy." (PMID 36524130, 2022). "Subsequently, a prominent increase in KIF20A expression was observed in several malignancies, such as lung, breast, gastric, liver, bladder, and pancreatic cancers." (PMID 36096734, 2022). "In 2015, upregulation of KIF20A was first identified in pancreatic cancer, and KIF20A inhibition appeared to significantly inhibit the proliferation of pancreatic cancer cells." (PMID 36096734, 2022). "Kif20a expression has been identified as a prognostic indicator for ovarian clear cell carcinoma 9, nasopharyngeal cancer 10 and pancreatic cancer." (PMID 32742456, 2020). "KIF20A serves a key role in malignant biological behaviors, including invasion and metastasis of pancreatic carcinoma cells." (PMID 32963620, 2020). "Inhibition of the pancreatic carcinoma RAB6KIFL/KIF20A cell line by small interfering RNA targeting KIF20A can significantly inhibit the proliferation of this cell line." (PMID 32963620, 2020).
pancreatic cancer (continued). "In 2005, scientists first discovered that KIF20A is overexpressed in pancreatic cancer and silenced KIF20A with siRNA to inhibit the growth of pancreatic cancer cells." (PMID 31093305, 2019). "If the expression of KIF20A is downregulated, there is a significant reduction in the proliferation of pancreatic cancer cells." (PMID 31093305, 2019). "KIF20A expression is aberrant in various cancers, such as cervical squamous cell carcinoma, pancreatic cancer and glioma." (PMID 31788359, 2019). "A phase I clinical trial based in Japan combined a KIF20A-derived peptide with gemcitabine (GEM) in patients with advanced pancreatic cancer who had received prior chemotherapy and/or radiotherapy." (PMID 28081138, 2017). "Vaccination with a KIF20A-derived peptide in combination with gemcitabine is a feasible and promising approach to the treatment of advanced pancreatic cancer." (PMID 25652119, 2015). "In this report, we further demonstrated non-randomized, open-label, single centered phase I/II clinical trial of immunotherapy using the KIF20A-66 peptide for the patients with advanced pancreatic cancer." (PMID 24237633, 2013). "KIF20A, kinesin family member 20A, is one of the candidates of such target antigen, as it was up-regulated in the majority of pancreatic cancer." (PMID 24237633, 2013). "We here report the results of a phase I/II clinical trial using KIF20A-66 mono peptide as cancer immunotherapy for the patients with advanced pancreatic cancer." (PMID 24237633, 2013). "KIF20A-66 is HLA-A24-restricted epitope peptide derived from KIF20A, a member of kinesin super family protein 20A that is significantly transactivated in pancreatic cancer." (PMID 24237633, 2013). "Taken together, we concluded that the cancer vaccination utilizing KIF20A-derived peptide was significantly effective as immunotherapy against advanced pancreatic cancer." (PMID 24237633, 2013). "Further investigation of the capability for induction of KIF20A-specific CTLs in pancreatic cancer patients thus remains an issue of great importance for clinical application." (PMID 21179034, 2011). "Last, KIF20A plays a role in cytokinesis and inhibiting expression of this gene attenuated growth of pancreatic cancer cells." (PMID 21931799, 2011). "On the basis of the genome-wide cDNA microarray analysis, we focused on KIF20A (also known as RAB6KIFL/MKlp2) as a candidate TAA in pancreatic cancer cells." (PMID 21179034, 2011). "In this study, we focused on KIF20A as another pancreatic cancer-specific TAA for immunotherapeutic target." (PMID 21179034, 2011). "The knockdown of KIF20A gene expression in pancreatic cancer cell lines by small-interfering RNA drastically inhibited the growth of those cells." (PMID 21179034, 2011). "As KIF20A is highly expressed in a wider range of human malignancies, KIF20A is therefore a promising target for peptide-based immunotherapy for the treatment of malignancies, especially pancreatic cancer." (PMID 21179034, 2011). "The KIF20A gene was overexpressed in pancreatic cancer cells but barely expressed in their normal counterparts and in many normal adult tissues as revealed by the cDNA microarray analysis, RT–PCR analysis, and immunohistochemical analyses." (PMID 21179034, 2011). "We then checked the expression of the KIF20A gene in surgically resected pancreatic cancer tissues and their adjacent normal counterparts by RT–PCR analyses." (PMID 21179034, 2011). "KIF20A is a novel promising candidate for anticancer immunotherapeutic target for pancreatic cancers." (PMID 21179034, 2011). "Both KIF20A and KRT6A were reported to be highly expressed in tumor tissues and associated with poor prognosis in multiple cancers, such as prostate, breast, gastric and pancreatic cancers." (PMID 34249701, 2021).
pancreatic cancer (continued). "A KIF20A-targeted polypeptide vaccine, which induces a specific immune response of cytotoxic T lymphocytes, has been developed and has achieved good results in the treatment of advanced pancreatic carcinoma." (PMID 32963620, 2020). "KIF20A has been studied extensively in pancreatic carcinoma." (PMID 32963620, 2020). "The down-regulation of KIF20A was previously demonstrated to markedly suppress pancreatic cancer cell growth, indicating that KIF20A might be an oncoantigen." (PMID 30380781, 2018). "KIF20A is involved in tumor progression and angiogenesis and was previously reported to be highly expressed in various cancers, such as non-small-cell lung cancer, pancreatic cancer, bladder cancer, and cholangiocellular carcinoma." (PMID 30380781, 2018). "In addition, knockdown of KIF20A gene in pancreatic cancer cells (PDAC) by siRNAs, inhibited their growth, implicating a vital role in cytokinesis and maintaining cellular viability." (PMID 28052097, 2017). "KIF20A was found to be consistently overexpressed in pancreatic cancer in several different high-throughput expression profiling analyses, and a previous study demonstrated that targeting KIF20A reduces the proliferation, migration and invasion of pancreatic cancer cells." (PMID 28081138, 2017). "KIF20A is overexpressed and represents a potential immunotherapeutic target in pancreatic cancer, and silencing KIF20A using a small interfering RNA inhibited the proliferation, motility and invasion of pancreatic cancer cell lines." (PMID 28081138, 2017). "Moreover, Array results showed that fisetin inhibited significantly KIF20A expression in both hepatic and pancreatic cancer cells." (PMID 28052097, 2017). "In this report, we demonstrated that the KIF20A-derived peptide could improve the prognosis of the patients with advanced pancreatic cancer, suggesting that the KIF20A peptide vaccination is a promising approach as cancer immunotherapy." (PMID 24237633, 2013). "Thus, we concluded that KIF20A-66 vaccination is significantly effective as an immunotherapy against advanced pancreatic cancer." (PMID 24237633, 2013). "We investigated nine samples of pancreatic cancer, and a strong staining of KIF20A was mainly observed in the cytoplasm and nuclei of cancer cells in six cases, whereas a very weak staining was observed in acinar cells and the normal ductal epithelium of their normal adjacent pancreatic tissues." (PMID 21179034, 2011). "Furthermore, the involvement of KIF20A in pancreatic carcinogenesis suggests that KIF20A would be a promising immunotherapeutic target for pancreatic cancer." (PMID 21179034, 2011). "Therefore, KIF20A-66 vaccine was effective for advanced pancreatic cancer." (PMID 36798768, 2023). "We previously reported that vaccination with KIF20A and VEGFR1 epitope peptides was safe and feasible for the treatment of patients with advanced pancreatic cancer." (PMID 24398900, 2014). "In this study, KIF20A-66 peptide was subcutaneously injected into metastatic pancreatic cancer patients who failed to treate with gemcitabine." (PMID 36798768, 2023). "The KIF20A-derived peptide vaccine induced high numbers of IFN-γ-producing cells, even in patients treated with GEM, suggesting this combination therapy holds promise for advanced pancreatic cancer." (PMID 28081138, 2017). "KIF20A was overexpressed in pancreatic cancer and in some other malignancies, but not in their non-cancerous counterparts and many normal adult tissues." (PMID 21179034, 2011). "This study analysed the gene expression profiles of pancreatic cancer using a genome-wide cDNA microarray consisting of 27 648 genes, which revealed that KIF20A was overexpressed in pancreatic cancer tissues but not in many normal tissues." (PMID 21179034, 2011). "The KIF20A gene was detected in five of eight pancreatic cancer tissues, whereas virtually no expression was observed in their normal counterparts." (PMID 21179034, 2011).
pancreatic cancer (continued). "However, there is no available AD-related information for the ESPL1, KIF20A, SPRR2G, and SPRR3 genes, which instead have associations with various cancers, including adenocarcinoma, medulloblastoma, tongue cancer, and pancreatic cancer, respectively." (PMID 39766348, 2024). "Thus, KIF20A mediated IGF2BP3 transport, promoted motility and invasiveness in pancreatic cancer." (PMID 36798768, 2023). "KIF20A may promote the motility and invasiveness of cancer cells by transporting the RNA-binding protein IGF2BP3 and its transcripts towards the cell protrusions along microtubules, as shown in pancreatic cancer cells." (PMID 27941992, 2016). "Similarly to pancreatic cancer cells, KIF20A-depleted MCF7 cells did not arrest in mitosis or display a multinucleated phenotype suggesting that other kinesins may have taken over its mitotic function in these cells." (PMID 23071517, 2012). "Although PZD has been reported to have antitumor efficacy in pancreatic cancer, there are no previous reports indicating AURKB or KIF20A inhibition as the possible mechanism for its effects." (PMID 34593983, 2023).
glioma (36 papers, 2018 to 2026). A benign or malignant brain and spinal cord tumor that arises from glial cells (astrocytes, oligodendrocytes, ependymal cells). "This study suggests the potential roles of a novel hypoxia‐associated CDC20+KIF20A+PTTG1+ cell subpopulation in glioma progression." (PMID 40047299, 2025). "Elevated KIF20A levels have been associated with advanced tumor grades and poorer prognosis in patients with glioma." (PMID 37744243, 2023). "Previous research has indicated that elevated expression of KIF20A is associated with an unfavorable prognosis in patients with glioma." (PMID 37744243, 2023). "It has been reported that the high expression of KIF20A is associated with poor prognosis of glioma patients, and KIF20A can be a potential immunotherapeutic target for glioma." (PMID 33726794, 2021). "We identified a unique CDC20+KIF20A+PTTG1+ high‐risk glioma cell subpopulation probably necessary for glioma progression of LGG/GBM transformation, which was further explored in multiple cohorts and validated in samples by immunohistochemistry and multiplex immunofluorescence assays." (PMID 40047299, 2025). "KIF20A deficiency can suppress the proliferation and migration of glioma cell." (PMID 39707577, 2024). "Finally, high expression of KIF20A is associated with an unfavorable prognosis in glioma, and its knockdown can inhibit the proliferation and migration of glioma cells." (PMID 37744243, 2023). "Hence, these results hint that CDC20+KIF20A+PTTG1+ high‐risk glioma cell subpopulation was specifically associated with hypoxia, which may drive this cell subpopulation predominantly via regulating its No.1 marker gene CDC20." (PMID 40047299, 2025). "In conclusion, these findings suggest that the CDC20+KIF20A+PTTG1+ cell subpopulation is critical to glioma progression." (PMID 40047299, 2025). "Abnormal expression of KIF20A has been observed in various cancers, including breast, pancreatic, glioma, hepatocellular carcinoma, esophageal squamous cell carcinoma, bladder, and prostate cancers." (PMID 40564876, 2025). "CDC20+KIF20A+PTTG1+ glioma cell subpopulation remains relative higher hypoxia level than other glioma cells in each time point, and increased during long‐term gliomagenesis." (PMID 40047299, 2025). "We firstly examined the expression of KIF20A in glioma, and we observed a significant upregulation of KIF20A in tumor tissue compared to normal tissue in the TCGA-LGG and TCGA-GBM cohorts (all p < 0.05)." (PMID 37744243, 2023). "In the study of glioma, ten patients received subcutaneous injection of mixtures including KIF20A peptide." (PMID 36798768, 2023). "Increased KIF20A accelerated the proliferation, invasion, migration, and inhibited apoptosis of glioma cells." (PMID 36798768, 2023). "In glioma, KIF20A promoted cell proliferation and invasion; down-regulated KIF20A reduced cell proliferation, induced apoptosis." (PMID 36798768, 2023). "Lastly, the effect of kinesin family member 20A (KIF20A) on the proliferation and migration of glioma cells was evaluated in vitro." (PMID 37744243, 2023). "A related study showed that tumor specimens from patients with glioma were used for gene sequencing and showed that patients with increased KIF20A expression had a poorer survival prognosis." (PMID 35774141, 2022). "Saito reported that KIF20A was significantly upregulated, particularly within glioma tissues, throughout the process of cellular mitotic activities." (PMID 34689806, 2021). "Circ-Serpine2 exacerbated the malignant progression of glioma mediated by the miR-124-3p/KIF20A nexus, thus providing novel predictive/prognostic biomarkers and drug targets against glioma." (PMID 34689806, 2021).